JAK1 (Janus kinase 1)
Diseases named in the same sentence as JAK1 in open-access papers (continued):
Sharing a sentence is not in itself a finding about the gene and the disease.
tumor (continued). "We therefore examined whether loss of JAK1 affects the apoptosis of B16/OVA tumor cells." (PMID 30837996, 2019). "Assuming that JAK1 deficiency in these cells was due to a gene mutation and concurrent allelic loss, we performed single-nucleotide polymorphism (SNP) array analyses on DNA obtained from the three tumour cell populations and autologous Epstein-Barr virus (EBV)-transformed B cells as a control." (PMID 28561041, 2017). "The IL-6/JAK1/STAT3 signal axis is implicated in promoting inflammatory responses and cellular proliferation, thereby influencing the tumor microenvironment and potentially exacerbating the susceptibility to gastric carcinogenesis." (PMID 41284643, 2025). "In our study, we found that combining a JAK1 inhibitor with EGFR‐TKIs treatment enhances tumour control." (PMID 40162549, 2025). "For instance, PTPN2, a phosphatase that dampens IFN-γ signaling through dephosphorylation of STAT1 and JAK1, negatively regulates tumor antigen presentation and impedes cytokine-driven tumor inhibition 73-75." (PMID 41281758, 2025). "Collectively, these data highlight the potent anti-tumor effects of the simultaneous inhibition of the Notch1 and JAK1/STAT3 pathways." (PMID 40019515, 2025). "Adaptive trial designs can facilitate the testing of agents that restore or bypass these pathways, such as epigenetic therapies that enhance antigen presentation or T cell activation, thereby improving outcomes in JAK1/2-mutant tumours." (PMID 40277912, 2025). "The latest research findings indicate that administering the Janus kinase 1 (JAK1) inhibitor itacitinib following anti-PD-1 (programmed cell death protein 1) immunotherapy enhances immune function and the anti-tumor response in mice." (PMID 40264452, 2025). "Consistent with our in vitro findings, Western blot analysis of tumor tissues revealed that CDN treatment downregulated p-JAK1/2 and p-STAT3 expression while upregulating the pro-apoptotic proteins Bax, cleaved caspase-3, and cleaved caspase-9." (PMID 41585878, 2025). "The levels of signal transducer and activator of transcription 3 (STAT3), phosphorylated‐STAT3 (p‐STAT3), Janus kinase 1 (JAK1), phosphor‐Janus kinase‐1 (p‐JAK1), and PD‐1 in tumor tissues were measured using Western blot (WB)." (PMID 39874200, 2025). "As a result, M2 macrophages promoted 5-fluorouracil (5-FU) resistance of tumor cells in a mechanism of CCL8 activation of JAK1/STAT3 signaling pathway in tumor cells." (PMID 40361394, 2025). "Another patient with a stage T3 tumor received golidocitinib (JAK1 inhibitor) combined with the chidamide regimen as a second-line therapy for two cycles at the last follow-up date, and the disease remained stable." (PMID 40427170, 2025). "We also investigated the impact of TAK-243 administration on JAK1 and MHC-I expression in tumor-associated macrophages." (PMID 39540840, 2025). "Oxymatrine (OMT), the oxide derivative of MT, inhibited tumor growth in a lung cancer xenograft model by blocking JAK1, JAK2 and Src kinase activation upstream of STAT5, thereby suppressing STAT5 phosphorylation." (PMID 40841966, 2025). "Current research is exploring strategies to restore or bypass these pathways, such as using agents that enhance antigen presentation or T cell activation, to improve outcomes in JAK1/2-mutant tumours." (PMID 40277912, 2025). "The immune escape from T cells caused by the knockout of genes IFN-γ signaling pathway (JAK1, JAK2, Ifngr2) and antigen presentation pathway (TAP1, TAP2, B2M) promotes tumor vulnerability to NK cells." (PMID 40191187, 2025). "IL‐10, secreted by tumor‐associated macrophages, stimulates cancer stem cell‐like characteristics in NSCLC cells via the JAK1/STAT1/NF‐κB/Notch1 pathway." (PMID 41223031, 2025).
tumor (continued). "PD-L1 is highly glycosylated in tumor cells to maintain its stability via IL-6/JAK1-mediated phosphorylation and subsequent glycosylation." (PMID 39996058, 2025). "Our study suggests that sequestration of IAP1 by LKB1 helps maintain a functional IFNγ-JAK-mediated immune response in LKB1-WT cells, whereas, in LKB1-mut cells, IAP1 directly impinges on JAK1 and impairs tumor immune response." (PMID 40057483, 2025). "In parallel, JAK1 and JAK2 hyperactivation is commonly linked to cytokine-driven signaling that sustains tumor growth, while TYK2 shows dual behavior: supporting immune surveillance in some contexts but fostering immune evasion in others." (PMID 41438753, 2025). "As expected, p-ACAP4Y843 and p-JAK1 were highly expressed in HCC tumor tissues compared with adjacent tissues." (PMID 39744421, 2025). "In vitro, BBR suppressed IL-4 or tumor cell supernatant-induced M2 polarization, as evidenced by decreased expression of M2 polarization marker genes (Arg1, Retnla, etc.)and reduced JAK1/STAT6 phosphorylation levels." (PMID 41585886, 2025). "Bufalin directly binds to JAK1 and suppresses hepatoma cell migration and tumor metastasis in HCC orthotopic xenograft mice." (PMID 39744421, 2025). "Taken together, these findings suggested that irisin, OSM, and GEN can impede tumor progression and shift towards M2 macrophages by suppressing the JAK1/STAT6 pathway." (PMID 40604704, 2025). "Subsequently, we explored the possibility of in vivo synergy between JAK1 inhibitors and osimertinib, utilising H1975 tumour cells integrated with either 3T3‐Cxcl14 vector or overexpression fibroblasts." (PMID 40162549, 2025). "The m6A modification of Jak1 mRNA in tumor-infiltrating myeloid cells (TIM) via METTL3 improves the translation efficiency of JAK1 protein and STAT3 phosphorylation." (PMID 39136000, 2024). "Next, we used subcutaneous tumor-bearing mice to further confirm the involvement of JAK1/PI3K/AKT axis in CTDSPL2-induced tumor growth." (PMID 39209829, 2024). "As demonstrated by western blotting, deletion of Jak1 abrogated PD-L1 expression, devoiding the tumor cell of a primary target of immune checkpoint blockade." (PMID 38427670, 2024). "Meanwhile, our research has unveiled the targeting agent EGR3 of C6 ceramide, which functions as a tumor suppressor gene by regulating the JAK1/STAT3 signaling pathway." (PMID 38338065, 2024). "Our research extends the understanding of p27 tumour suppressive function by revealing its inhibitory effect on the JAK1/STAT3 pathway." (PMID 39099000, 2024). "Jak1 further regulates the expression of chemokines driving tumor T cell infiltration, such as CXCL9, CXCL10 and CXCL11." (PMID 38427670, 2024). "Consistent with previous reports, we found enrichment of sgRNA targeting genes associated with both IFN-gamma signalling (Jak1, Jak2, Ifngr2) and TNF signalling (Tnfrsf1a, Fadd) in tumour cells resistant to CAR-T cell killing." (PMID 39261596, 2024). "In a tumor microenvironment, the transphosphorylation of JAK1, JAK2, and STAT1 led to the upregulation of PD-L1 expression." (PMID 39690423, 2024). "A tumor’s capacity to react to interferon-gamma (IFN-γ), a cytokine essential for immune-mediated tumor elimination, can be hindered by mutations in the JAK1/2 gene, for instance." (PMID 39273605, 2024). "As expected, our confocal microscopic data showed that MUC1-CT and p-JAK1 are co-localised in the cytoplasm of tumour cells, predominately close to the nucleus." (PMID 36810913, 2023). "The IL-6/JAK1 signaling pathway has been shown to positively regulate the stability of the PD-L1 protein and promote tumor immune escape." (PMID 37601051, 2023).
tumor (continued). "Biomarker analyses revealed high SV burden, JAK1 frameshift mutations and low IFN-γ expression as possible resistance mechanisms to anti-PDL1 in dMMR/MSI-H tumours, providing a rationale for larger studies to validate these findings." (PMID 36870947, 2023). "CRISPR–Cas9-mediated disruption of the Jak1 gene encoding for a central mediator of the IFN signalling pathway leads to IFN-unresponsive and completely MHC-deficient tumour cells." (PMID 37316667, 2023). "Numerous strategies have been evaluated to promote the anti-tumor potential of macrophages, such as the use of JAK1/2 inhibitor, ruxolitinib, to reverse M2 polarization in favor of the M1 phenotype in in vitro and in vivo MM models." (PMID 37445697, 2023). "Biomarkers, such as high PD-L1 expression or a significant tumor mutational burden (TMB), as well as genetic alterations like JAK1/2 mutations, are at the forefront of predicting and countering immunotherapy resistance." (PMID 38136402, 2023). "In patients receiving immunotherapy, tumor cells can downregulate or alter the IFN-γ pathway, such as loss-of-function alleles in the gene encoding JAK1/2 and alterations in STAT1, to evade the effects of IFN-γ and thus develop resistance." (PMID 37637050, 2023). "As a result of the administration of ruxolitinib (a JAK1/2 selective kinase inhibitor) in mouse models, a decline in tumor cell proliferation rate was reported, showing a positive correlation between JAK1/2 and disease progression in KRAS-mutant NSCLC." (PMID 36899885, 2023). "As expected, IHC staining of PDX tumor tissues indicated that siEHBP1L1 treatment led to decreased JAK1 protein level." (PMID 36775874, 2023). "TNFα is reported to synergize with IFNγ to induce Jak1/Stat1-dependent tumor cell death and recruit cytolytic T cells to the tumor microenvironment." (PMID 36968224, 2023). "Ptpn2-mediated dephosphorylation of Stat1 and Jak1 negatively regulates signaling induced by IFNγ, a potent inhibitor of tumor growth via stimulation of the antitumor immune response." (PMID 36968224, 2023). "JAK1 inhibition with itacitinib (INCB039110) demonstrated reduced tumor volume in the immunocompetent, syngeneic PAN02 pancreatic cancer murine model." (PMID 38115208, 2023). "Once IL-6 binds to its receptor on the plasma membrane of tumor or stroma cells, the pathway JAK1/STAT3 is activated and controls genes involved in proliferation, survival, invasion and metastasis formation." (PMID 36639824, 2023). "IHC staining assays demonstrated that knocking down LINC00659/ALKBH5 decreased JAK1 expression in tumours, while overexpressing LINC00659/ALKBH5 increased the expression of JAK1." (PMID 36864711, 2023). "Sections of tumour xenografts from ALKBH5‐overexpressing or ALKBH5‐overexpressing BGC‐823 cells with LINC00659/JAK1 knockdown subcutaneously injected into nude mice were stained with JAK1 antibodies." (PMID 36864711, 2023). "In tumor-infiltrating myeloid cells H3K18 lactylation increased N6-adenosine-methyltransferase 70 kDa subunit (Mettl3) expression that modified Jak1 mRNA, thereby strengthening the immunosuppressive functions." (PMID 37584553, 2023). "The deactivation of JAK1 and JAK2 signaling led to acquired resistance to IFN‐γ, subsequently causing damage to immune surveillance and tumor cell proliferation." (PMID 37386520, 2023). "Thirteen kinases differentially expressed at the protein level in GAC tumor tissues with lymph node metastasis were plotted in a heatmap, including known drug targets JAK1, MAP3K4, and PRKCB, among others." (PMID 36520032, 2023).
tumor (continued). "METTL3 has also been found to direct the m6A methylation of JAK1 mRNA in tumor-infiltrating myeloid cells (TIMs), and the m6A/YTHDF1 axis has been shown to promote JAK1 translation." (PMID 37217462, 2023). "Nevertheless, both CD4 and CD8 ACT therapies substantially increased the number of myeloid cells in HCmel12 CRISPR-ctrl and HCmel12 Jak1-KO tumours." (PMID 37316667, 2023). "For further investigation of the relationship between ALKBH5/LINC00659 and JAK1 in the GC, we validated the JAK1 expression in tumours harvested from nude mice with LINC00659/ALKBH5 abnormally expressed and the paired controlled ones." (PMID 36864711, 2023). "JAK1 LOF mutations, including truncating and frameshift mutations, facilitate tumorigenesis via tumor immune evasion in EC." (PMID 36376931, 2022). "Expression levels of the tumor cell–autonomous gene IFNGR1 and downstream signaling axis and effector genes, including JAK1, JAK2, and IRF1, were all significantly lower in PRC2-loss tumors than in PRC2-wt tumors (P < 0.05)." (PMID 35852856, 2022). "The Jak2 kinase activity is also required for tumor progression, as treatment of Pax5Jak2/+ tumor‐bearing mice with the JAK1/2 inhibitor ruxolitinib delayed tumor growth leading to prolonged survival." (PMID 35156727, 2022). "In summary, IL-6 serves as a critical factor involved in the immunosuppression of T cells and tumor cells mediated via the IL-6/JAK1/Stat3 signaling pathway." (PMID 35550592, 2022). "Incubating tumor cells in osteoclastic CM led to a noticeable rise of JAK1 and STAT3 phosphorylation in IL20RB-overexpressing A549 cells, but not in control A549 cells." (PMID 36006737, 2022). "Consistent with the IHC results, human PCa tumor samples exhibited a significant enhancement in the expression of JAK1 and STAT1 compared to that observed in benign tissues." (PMID 36065066, 2022). "Tumor-infiltrated T helper 2 (Th2) cells produce IL-4 and IL-13 to activate Janus kinase 1 (JAK1)- signal transducer and activator of transcription 6 (STAT6)-MYC axis and enhance glycolysis, thus promoting tumorigenesis." (PMID 36230914, 2022). "Results in vitro showed that PD-L1 expression in the tumor was enhanced by IL-6 via the JAK1/Stat3 pathway, which induced immune evasion." (PMID 35550592, 2022). "This implies that the inactivation mutations of JAK1 and JAK2 block the IFN-γ signaling pathway, leading to downregulation of tumor PD-L1 expression, so it would be unnecessary to attempt anti-PD-L1 therapy in this case." (PMID 35740594, 2022). "Taken together, these results indicate that JAK1 acts as a tumor suppressor to negatively regulate EC cell growth and migration." (PMID 36376931, 2022). "In conclusion, the present study revealed the crucial role of LXN in tumor tumorigenesis from an immunological perspective, and its ability to regulate tumor microenvironment through modulating JAK1/STAT3/PD-L2 axis in macrophages." (PMID 36323670, 2022). "Formonetin inhibits cell proliferation, tube formation, and cell migration and interferes with MYC and STAT3 proteins via the RAS/ERK and JAK1/STAT3 pathways to suppress PD-L1 protein expression thereby promoting tumor cell apoptosis." (PMID 36452480, 2022). "Osteoclasts secrete IL-19 ligands to act on the IL-20RB of tumor cells, thus activating the JAK1/STAT3 signaling pathway to promote proliferation of disseminated tumor cells and colonization in bone." (PMID 36006737, 2022). "Tumor cells evade IFN-γ by downregulating or mutating the molecules involved in the IFN-γ signaling pathway, such as JAK1/2 and STAT, thus blocking the IFN-γ signaling pathway." (PMID 35740594, 2022). "We concluded that the inhibitory effect of JAK1 was responsible for the stronger anti-tumor properties of AZD3759 compared to those of osimertinib." (PMID 34738874, 2022).
tumor (continued). "Another possible explanation is that cancer cells exert genetic mutation in IFN-γ related signaling pathways Janus kinase 1 (JAK1) or Janus kinase 2 (JAK2), which make cancer cells less susceptible to T cell-mediated IFN-γ tumor suppression." (PMID 33514004, 2021). "In prostate cancer, epigenetic silencing of the crucial component JAK1 kinase of the IFNγ signaling pathway led to IFNγ-insensitivity-mediated tumor evasion and resistance to immunotherapy." (PMID 33406696, 2021). "It is also possible that these cells are functionally suppressed in the tumor microenvironment (e.g., mutations in JAK1 and JAK2 genes in tumor cells can lead to inappropriate antigen presentation)." (PMID 34502043, 2021). "JAK1 and SPEN were the top two gene mutations in primary tumors associated with tumor recurrence [OR = 7, 95% CI: 0.71, 69.49]." (PMID 34729947, 2021). "We evaluated the differences in JAK1 expression in various human tumour tissues and paired normal tissues using RNA sequencing data from the TCGA." (PMID 34587898, 2021). "Although well reported for its functions in tumour proliferation, survival, invasion and immunosuppression, JAK1/STAT3 signalling also contributes to drug resistance in NSCLC." (PMID 33523587, 2021). "Like Jak1/2 and B2m, Ankrd52 sgRNAs exhibited time-dependent enrichment in tumor cells in the presence of T cells, providing direct evidence that loss of ANKRD52 conferred resistance to T cell killing." (PMID 34853298, 2021). "In NSCLC cells, IL-6 neutralizing antibodies have been shown to inhibit tumor growth in mouse transplanted tumor models by inhibiting JAK1/STAT3 signaling." (PMID 34079469, 2021). "In pancreatic cancer, IL-6 not only promotes the occurrence and progression of tumours through JAK1/STAT3 but also activates reactive oxygen species through the ERK pathway." (PMID 34776511, 2021). "In NKTCL, frequent STAT3/5B activating mutations were detected in primary patient samples and cell lines, and JAK1/2/3 inhibitors potently suppressed cellular proliferation, inhibited tumor growth and induced apoptosis via abrogation of JAK/STAT program." (PMID 34680295, 2021). "After phosphorylation by JAK1/2, they promote tumor immunogenicity by upregulating MHC and immune checkpoint proteins (such as PD-L1 and B7-1) through STAT1 signaling of transcription factors." (PMID 34838003, 2021). "Oxymatrine plays a significant role in regulating cell proliferation and survival in tumor cells by inhibiting the activation of JAK1 and JAK2, thereby inhibiting the phosphorylation and nuclear translocation of STAT5." (PMID 34809653, 2021). "In the present study, we investigated the effects of Anwulignan treatment on the growth of NSCLC cells and tumours and its role in modulating the JAK1/STAT3 signalling pathway." (PMID 33523587, 2021). "Although they were adjusted for tumour purity, most immune markers remained significantly related to JAK1 expression levels in LUAD and LUSC." (PMID 34587898, 2021). "Inhibition of JAK1/2 signalling was shown to enhance osimertinib’s potency in EGFR‐driven NSCLC xenograft models, including tumours with the therapy‐resistant EGFR T790M mutation." (PMID 33523587, 2021). "For example, the inhibitors targeting the JAK1/STAT3 pathway play a role in both tumor cells and CAAs." (PMID 33413697, 2021). "According to an in vivo study of Jun Liao etal, the tumor suppression effect of NC was also attributed to the JAK1/STAT3 cascade signaling inhibition." (PMID 32931665, 2020). "Consistent with our previous observations, IFNγR2- and Jak1-mutant B16F10 tumors also exhibited slower tumor growth, although the difference in growth rate was less pronounced presumably due to decreased antigenicity." (PMID 32001684, 2020). "The expression levels of JAK1 in tumor and adjacent normal tissues of various cancers were analyzed based on the Oncomine database." (PMID 33323549, 2020).